TNF (tumor necrosis factor)
Diseases named in the same sentence as TNF in open-access papers (continued):
Sharing a sentence is not in itself a finding about the gene and the disease.
tumor (continued). "What’s more, the CAM NPs could increase the levels of tumor necrosis factor-α (TNF-a), interferon-γ (IFN-γ), and interleukins (IL-2 and IL-6), which further promote the tumor-infiltrating of T cells inducing prominently enhanced immune response." (PMID 36765543, 2023). "TNF is a cytokine that can directly kill tumor cells and exhibits no obvious toxic effect on normal cells." (PMID 37565866, 2023). "Tumor-derived PGE2 and TGF-β synergistically inhibit IFN-α and TNF-α production in stimulated pDCs." (PMID 37817484, 2023). "All non-PBS experimental groups produced detectable TNFα and IL-6 in the plasma from day 5 to day 26, suggesting the activation of human neutrophils upon tumor stimulation." (PMID 37080958, 2023). "Moreover, it has been shown that levels of serum TNF-α, IL-2, and serum CD44 (sCD44) are all increased in NHL and correlate with tumor burden, the presence of symptoms, and other clinical and laboratory variables." (PMID 36831345, 2023). "This is in line with a retrospective study investigating the tumor resistance mechanism after immunotherapy where the authors found that autophagy limits TNFα dependent activation of caspase 8 without modulating NF-κB pathway activity." (PMID 38071322, 2023). "On the other hand, the reduction of tumor growth through the production of tumor necrosis factor alpha (TNFα) by myeloid cells and T cells was shown in mice not receiving antibiotics." (PMID 38046824, 2023). "In line, analysis of culture supernatants by Legendplex assays showed a significant increase in IL-2, IFNγ, IL-10 and TNF secretion after treatment with 1 nM CC-3, but not with the isotype control or when target antigen negative tumor cells were used." (PMID 37122707, 2023). "Moreover, tumor-derived TGF-β and TNF-α synergistically inhibit IFN-I and TNF-α production through blocking interferon regulatory factor 7 (IRF7) expression and nuclear translocation." (PMID 37817484, 2023). "Therefore, mRNA expressions of chemokines CCL2, CCL17 and CCL22, as well as IL-6, IL-18, TNF-α and IFN-γ, in tumor tissues and H22 cells were detected by RT-qPCR." (PMID 36674931, 2023). "Furthermore, treatment with C. versicolor aqueous extract resulted in significant immunomodulatory effects, which were reflected by increased IL-2, IL-6, IL-12, TNF-α, and IFN-γ production in the spleen lymphocytes of C. versicolor-treated tumor-bearing mice." (PMID 37373268, 2023). "Unlike TNF-α, the tumor markers showed differences between G1 and G3, with higher levels for G3 tumors, but still exhibited much lower values compared to G2." (PMID 38137862, 2023). "Moreover, the tumor sections were stained with a CD31 antibody to investigate the therapeutic effect on the tumor vasculature since the RGD4C.TPA also targets the abnormal tumor blood vessels and TNFα was reported for its antiangiogenic activity." (PMID 37331004, 2023). "When assessed in vivo, the OV-CXCL11 and CAR T-cell combination further diminished tumor volume, significantly prolonged survival, increased CAR T-cell infiltration, and increased proinflammatory cytokine production (TNF-α and IFN-γ) compared to monotherapy alone." (PMID 38136398, 2023). "In addition, tumour-infiltrating macrophages secrete inflammatory factors and cytokines, such as TGFβ, IL-6, IL-10, and tumour necrosis factor α (TNFα), which promote EMT, have been shown to enrich tumours with CSC-like properties." (PMID 37174052, 2023). "Besides, NK cells can inhibit tumor growth by inducing pro-inflammatory cytokines, which include IFN-α, TNF-α, and granulocyte macrophage colony-stimulating factor." (PMID 37513975, 2023). "The molecules secreted by both tumoral and non-tumoral cells, such as VEGF, FGF, EGF, IL6, TNFα, and immune checkpoint molecules, contribute to the crosstalk between the tumor and its microenvironment." (PMID 37958474, 2023).
tumor (continued). "Inflammatory cytokines including TNF-α, IL-6, IFN-γ, and chemokines could exert antiproliferative and pro-apoptotic effects on tumor cells, or indirectly modulate the TIME." (PMID 37190266, 2023). "Th1 cells suppress malignant tumor proliferation via inducing an immune response to tumors by mainly secreting interferon‐γ (IFN‐γ) and tumor necrosis factor‐α (TNF‐α); while Th2 cells mainly secrete interleukin‐4 (IL4), IL‐10 leading to tumor immunosuppression." (PMID 37096492, 2023). "Hyperthermia stimulates the secretion of pro-inflammatory factors, including IL-1, interferon-γ, and tumor necrosis factor (TNF)-α, which are capable of directly destroying tumor cells and activating antigen-presenting cells (APCs) to attract them to the tumor site." (PMID 37869003, 2023). "Manipulated TAMs thus gain secretion of various tumor-promoting factors including CCL18, IL-10, and TGF-β while inhibiting the release of cytotoxic factors like IL-2, IL-12, TNF-α, and IFN-γ, impeding the anti-tumor capacity of other immune components and prolong tumor survival." (PMID 38274812, 2023). "In addition, YFJP significantly reduced the expression of inflammatory and immunosuppressive cytokines, including IL-1β, IL-6 and IL-10, while increased the expression of cellular effectors TNF-α and IFN-γ in serum and tumor tissues." (PMID 37355637, 2023). "In the hypoxic tumor micro-environment, pro-inflammatory factors such as tumor necrosis factor-α (TNF-α) and interleuin-6 (IL-6) were produced as a result of tissue damage and/or tumor necrosis, which might further activate the systemic inflammatory response." (PMID 37578602, 2023). "Meanwhile, TNF-α is also intimately correlated to the prognosis of NSCLC patients in the promotion of inflammation, epithelial–mesenchymal transition, invasion, and metastasis under a tumor microenvironment." (PMID 37765264, 2023). "Likewise, the inhibition of catabolic pathways (IL-6, TNF-alpha), balanced with the stimulation of anabolic pathways (FoxO3a, p-AKT, p-mTOR, and P-GSK-3β), has occurred in the counteraction of tumor-induced cachexia." (PMID 38004420, 2023). "To date, tumor-derived secreted cytokines, such as vascular endothelial growth factor (VEGF), tumor necrosis factor (TNF), stromal cell-derived factor 1, and transforming growth factor-β (TGF-β), which form premetastatic niches, induce the mobilization of bone marrow-derived cells." (PMID 36932197, 2023). "In addition, TNF-α upregulated the levels of VEGFC and D2-40 in tumor tissues compared with the control group." (PMID 37124061, 2023). "In addition to promoting tumor growth by secreting MMP-9 and TNF, NTLS-DCs further inhibit CD8+ T-cell activity by the L-arginine pathway and trigger Treg responses by secreting TGF-." (PMID 37842234, 2023). "The upregulation of TNF-α, IL1β, and Bcl-2 genes suggests that the CLT was able to initiate an inflammatory response to combat the tumor, while the downregulation of the Bax and Beclin1 genes indicates that the CLT was able to reduce the risk of apoptosis in the liver." (PMID 37160480, 2023). "An IMC-based analysis of resection specimens from 12 patients with LUSC identified a novel population of CD3-CD4+FoxP3+CD25-CD127- cells in both tumour and adjacent regions of 10 patients, which were also TNF-α-positive and IFN-γ-negative." (PMID 37835491, 2023). "In addition, PTX@CAR-Exos reprogrammed the tumor microenvironment and reversed the immunosuppression, which was attributed to infiltrating CD8+ T cells and elevated IFN-γ and TNF-α levels." (PMID 37308954, 2023). "However, simultaneously, they share the same MOAs; one is cell contact-dependent (direct) tumor cell killing via granzyme B, and another one is cell contact-independent (indirect) tumor cell killing via IFN-γ and TNF-α." (PMID 37100864, 2023).
tumor (continued). "Combined ATRA and anti-PD-L1 therapies may be promising approaches to CC cancer immunotherapy, as this approach delays tumor growth and increases antitumor T-cells, IFN-γ, and TNF-α levels." (PMID 37508372, 2023). "The level of hypoxia and angiogenic growth factors, such as basic fibroblast growth factor (bFGF), tumor necrosis factor α (TNF α) and vascular endothelial growth factor (VEGF), may also determine the expression of APN/CD13 on tumor cells." (PMID 37760428, 2023). "Furthermore, previous studies have indicated that TNF-α is involved in epithelial-mesenchymal transition (EMT), thereby promoting tumor metastasis." (PMID 38406175, 2023). "Moreover, various inflammatory and angiogenic cytokines, e.g., TNF-α, interferon-γ and VEGF etc., secreted from tumor tissue, flow into the circulation, suggesting an effect on the WSD of systematic viscera or vasculartures in tumor-bearing bodies." (PMID 37759649, 2023). "In line with this, treatment of mice bearing the Arf1‐ablated tumor cells with anti‐IFNAR1 and anti‐IL‐1β antibodies had markedly reduced frequency of the TNF+IFNg+PD1+CD8+ T cells in tumors in comparison with those in tumors treated with the isotype control antibody." (PMID 37786300, 2023). "Pro-tumor N2 neutrophils are known to influence cancer progression by the secretion of C-X-C motif chemokine ligand 1 (CXCL1), matrix metallopeptidase 9 (MMP-9), VEGF, and TNF-alpha, as well as ROS and NO." (PMID 37427115, 2023). "This conclusion is further supported by our observation that stimulation of HDMECs with the pro-angiogenic factors VEGF, EGF, bFGF, IL-6, and TNF-α, which are known to be secreted by tumor cells, has no influence on the expression of endothelial miR-186." (PMID 36845338, 2023). "Interestingly, the ratio of TNFα+ CD4+ to IL-17A+ CD4+ T cells was also skewed towards more IL-17A+ CD4+ T cells in the tumor tissues versus STM while the ratios of IFNγ+ CD4+ and TNF+ CD4+ T cells showed a small change towards more TNFα." (PMID 38074634, 2023). "In summary, RNF31 was correlated with TNF and IFN-γ pathways, suggesting RNF31 may affect tumor immunity by participating in these cytokine-related pathways." (PMID 37117215, 2023). "Notably, we observed a high abundance of TNF/TNFR ligand-receptor pairs between B cells and tumor-infiltrating T cell subgroups." (PMID 38149239, 2023). "TGF-β inhibition enhanced the proinflammatory potential of TANs (N1), resulting in an increased expression of proinflammatory cytokines such as TNF-α and CCL3, cytotoxic CD8+ T lymphocyte activation, and direct killing of tumor cells dependent on ROS and the costimulatory molecule ICAM-1." (PMID 37298230, 2023). "Enrichment of VEGFC in the GC microenvironment could induce lymphangiogenesis, while increased CCL5 in tumor microenvironment could form a concentration gradient to recruit M2 type TAM, then promote TNF‐α secretion to increase lymphatic permeability." (PMID 37409440, 2023). "Only one study mentioned that TNF-α can activate p65 to directly activate NF-κB signaling, leading to the release of the pro-inflammatory and pro-cancer factors, CCL-2 and CCL-8, in the inflammatory tumor microenvironment." (PMID 36814921, 2023). "The TNF-α targets downregulated by Ent include LIF, a pro-tumorigenic cytokine that triggers tumor STAT3 pathway and contributes to PDAC progression and therapeutic resistance, indicating the potential of HDACi to reduce the pro-tumorigenicity of CAF secretome." (PMID 38057326, 2023). "Then, strong and sustained cytotoxicity on a panel of different target cancer cells and increased release levels of IFN-γ and TNF-α were found in normal donor PBMC-derived B7-H3 CAR T cells or CSPG4 CAR T cells, respectively, following repetitive co-culture with stressed tumor cells." (PMID 37714830, 2023).
tumor (continued). "Consistent with the previous results, IRU CAR-T (+CsA) group showed a significantly higher frequency of IFNγ+TNFα+-secreting CAR-T cells than that in WT CAR-T (+CsA) group, supporting that IRU CAR-T could better control tumour progression with CsA." (PMID 38123592, 2023). "However, significantly more tumor cell deaths and less secretions of cytokines (IL-6, IFN-γ, granzyme B and TNF-α) from the medium were observed in CRC cells with A20 overexpression than that in control cells and PBMCs co-culture system with matched HLA-A2." (PMID 37607946, 2023). "Moreover, circCRIM1 overexpression increased the infiltration proportion of Granzyme B, IFN-γ, and TNF-α positive CD8+ T cells and NK cells in the subcutaneous tumor via flow cytometry." (PMID 36672208, 2023). "However, a preclinical study revealed that the treatment with anti-mouse TNFR2 surrogate antibody (suAb) abrogated TNF-induced expansion of Tregs in vitro and decreased expression of PD-1 on CD8 tumor-infiltrating lymphocytes (TILs) in vivo." (PMID 36865537, 2023). "When incubated with tumor cells, EGFR CAR-E27-CCR6 T cells specifically exerted potent cytotoxicity and produced high levels of pro-inflammatory cytokines, including tumor necrosis factor-α (TNF-α), interleukin-2 (IL-2), and interferon-γ (IFN-γ)." (PMID 36982500, 2023). "Similarly, the synergy between 1.5 ng/ml TNF-α and 6.5 ng/ml IFN-γ (or 15 ng/ml TNF-α and 65 ng/ml IFN-γ) led to the polarization of bone marrow MSCs towards the pro-inflammatory Th1 phenotype, thus amplifying the anti-tumor immune response." (PMID 36814921, 2023). "In addition, invasion by these intestinal microorganisms promotes the differentiation of CD8+ T cells into cytotoxic T-lymphocytes, which produce IFN-γ, tumor necrosis factor alpha (TNF-α), and Fas ligand to kill tumor cells." (PMID 36950522, 2023). "Concomitantly, a sandwich ELIZA for pro-inflammatory cytokines (TNF-α, IL-1β, IL-6 and IL-12) revealed a dose-dependent reduction in levels of pro-inflammatory cytokines (p<0.05 and p<0.001) of ART-treated tumor-bearing mice compared to the untreated tumor-bearing mice." (PMID 38144525, 2023). "Evaluation of cytokine changes in the tumor microenvironment by ELISA-based analysis of tumor lysates demonstrated that combined blockade elevated the levels of cytokines IFN-γ, TNF-α, IL4, M-CSF, GM-CSF, and CCL2, while it suppressed the immune suppressive cytokine TGF-β." (PMID 37449205, 2023). "In certain tumor systems, both TGF-β and TNF-α have been shown to inhibit eAGR2 expression." (PMID 37175601, 2023). "Accumulated lipids, particularly oxidized low-density lipoprotein (ox-LDL), can increase intracellular LPO levels, ultimately resulting in ferroptosis and reducing the production of anti-tumor factors such as IFN-γ and TNF-α by activating p38, thereby impairing anti-tumor immune responses." (PMID 37700339, 2023). "TAK1 (MAP3K7) is a key regulator of TNFα induced signaling controlling the balance between cell survival and death which was found in our killing screen as well as in other CRIPSR KO screens investigating tumor resistance mechanisms to CTL-mediated killing." (PMID 37732732, 2023). "Furthermore, DEXs can activate NK cells and trigger caspase-mediated tumor cell apoptosis in vitro by expressing tumor necrosis factor-related apoptosis ligand (TRAIL), tumor necrosis factor (TNF), and FasL." (PMID 37631284, 2023). "In addition, the KEGG analysis revealed several pathways potentially involved in tumor pathogenesis and progression, such as the PI3K-Akt signaling pathway, TNF signaling pathway, and Toll-like receptor signaling pathway." (PMID 37790935, 2023). "IL-10 may decrease the production of proinflammatory cytokines such as IL-6, TNF-α, and IFN-γ and thus promote polarization of macrophages toward the protumorigenic M2 phenotype and thus ultimately enable tumor cells to evade immune surveillance." (PMID 38033495, 2023).
tumor (continued). "Moreover, importantly, combination of RGD4C.TPA.TNFα with CDDP resulted in further antitumor effects and reduction in tumor size and tumor viability, when compared to RGD4C.TPA‐TNFα‐ or CDDP‐treated groups." (PMID 37331004, 2023). "Similarly, iNos, IL-1b, and TNFα expression was increased in responder-derived TES-treated macrophages, indicating the enhanced anti-tumor activity of macrophages for inducing T cell immunity." (PMID 36707872, 2023). "Factors involved in tumor-mediated NET formation include tumor-derived inflammatory and chemoattractant cytokines (IL-8, IL-6, TNF-α, G-CSF and IL-1β), tumor extracellular vesicles, tumor-activated platelets, tumor-derived HMGB1, KRAS oncogene mutation and hypoxia." (PMID 37511453, 2023). "Furthermore, certain cytokines/chemokines like TNF-α, IL-18, and RANTES are believed to contribute directly to tumor growth by stimulating receptors on tumor cells." (PMID 38247456, 2023). "The increased cytotoxicity of PDT mediated by the production of nitric oxide, interleukin-6 (IL-6), and tumor necrosis factor alpha was in turn achieved in the presence of non-resident macrophages with a strong anti-tumor phenotype (TNF-α)." (PMID 38201494, 2023). "Furthermore, CD4+ cells directly kill tumor cells via the secretion of effector molecules, such as cytokines (IFN-γ and TNF-α), upon DC activation." (PMID 38328405, 2023). "GSDMB can be induced by interferon gamma (IFN-γ) and tumor necrosis factor alpha (TNF-α), which could be released by tumor-infiltrating CD8 T cells and other immune cells, thus providing a positive feedback loop." (PMID 36742298, 2023). "Tumor tissues with high DSE expression showed higher levels of IFNG, GZMB, and TNF expression." (PMID 37833287, 2023). "Inflammation is an effective inducer of EMT in tumors, TGF- β, TNF-α, IL‐1β, IL-6, IL-8, and other proinflammatory cytokines play a role in the initiation and maintenance of tumor EMT, increasing the invasiveness of cancer cells and promoting tumor metastasis." (PMID 37213276, 2023). "Many studies have uncovered that certain microbes could not only influence cytokines such as IL‐6 and TNF‐a directly or indirectly, but also activate the NF‐κB pathway or STAT3 pathway to promote tumor progression." (PMID 38868430, 2023). "Furthermore, activated neutrophils enhance the expressions of the TNF and FASL, resulting in their increased infiltration in a tumor area, and thus eventually leading to tumor cell clearance." (PMID 37444436, 2023). "In conclusion, CPG administration could remarkably inhibit the transplanted tumor growth in mice with an inhibitory ratio of 45.37% and significantly improve the expression of IL-2, IFN-γ, and TNF-α." (PMID 37958581, 2023). "By blocking TNF- α, the promotion of TNF- α on tumor can be reduced." (PMID 37006260, 2023). "A total 40 μg of GSDMBNT mRNA@LNPs was intratumorally injected into 4T1 tumors and then the concentrations of inflammatory cytokines including tumor necrosis factor-alpha (TNF-α) and interferon-gamma (IFN-γ) in tumor tissue or serum were assayed by ELISA after 6, 24, or 72 h, separately." (PMID 37454146, 2023). "Surprisingly, we found that TNFR1 deficiency, either tumor cell-intrinsic or systemic, did not affect SCLC development, in contrast to the important role of TNF signaling in other types of cancer." (PMID 36653597, 2023). "In our study, CCL2 at concentrations secreted by tumor cells did not affect murine mBMM survival or TNFα secretion and an analysis of CCL2s impact on these readouts did not change in the context of different matrix substrates." (PMID 37176074, 2023). "Experiments were performed both with and without added TNF-α (10 ng/mL) to represent external TNF-α activation in the tumor microenvironment." (PMID 36831656, 2023).